ENSG00000252020
Synonyms: LOC124905172
Gene: Small Cajal body-specific RNA gene on chromosome 22 (21,389,796 to 21,389,938, reverse strand). Ensembl gene ENSG00000252020.
Gene Ontology:
Biological process: RNA processing
Cellular component: Cajal body; nucleolus